CCL26 (C-C motif chemokine ligand 26)
Diseases named in the same sentence as CCL26 in open-access papers (continued):
Sharing a sentence is not in itself a finding about the gene and the disease.
eosinophilia (12 papers, 2014 to 2025). "Plasma CCL26 levels may be a useful biomarker for eCRSwNP because they are associated with NP tissue eosinophilia and plasma TSLP and IL-33 levels in patients with eCRSwNP." (PMID 40919679, 2025). "As the major effector cytokine in EoE, IL-13 stimulates epithelial production of eotaxin-3 (aka CCL26), a potent chemoattractant for eosinophils and basophils, and promote tissue eosinophilia." (PMID 30101408, 2019). "Epithelial cells of Socs1−/−MGLtg mice produce more CCL26 which in turn attracts eosinophils resulting in airway eosinophilia." (PMID 27917175, 2016). "IL-5 promotes eosinophilia, and IL-4 and IL-13 enhance the production of eosinophil chemoattractants (CCL11/eotaxin-1, CCL24/eotaxin-2, and CCL26/eotaxin-3) and activate B cells, macrophages, fibroblasts, epithelial cells, and goblet cells." (PMID 37674852, 2023). "The results revealed that unlike IFN-γ, IL-4, IL-5, IL-13, ALOX15, CST1, POSTN, and CCL26 were significantly elevated in patients with eosinophilia greater than 5%." (PMID 40978168, 2025). "Serum miR-1 levels were inversely correlated with tissue eosinophilia in samples from patients with CRSwNP, and miR-1 recruited TSLP (and P-selectin, CCL26 [eotaxin-3], and thrombopoietin receptor) to the RNA-induced silencing complex and downregulated these genes." (PMID 40919679, 2025). "IL-4, IL-5, IL-13, ALOX15, CST1, POSTN, and CCL26 were significantly elevated in patients who had eosinophilia higher than 5%, but not IFN-γ." (PMID 40978168, 2025). "All immune constituents contributed to the model but some, identified by variable-important-in-projection values > 1 and p < 0.1, contributed more strongly, including BAL Th1 and Th2 cells and eosinophilia, CCL26 (Eotaxin 3), IgA and IL-19 concentrations in blood." (PMID 34349761, 2021). "Why CCL26 expression should be down-regulated, whilst tissue eosinophilia was increased, is not clear, but it does add further evidence to suggest that dietary GP modulates eosinophil homeostasis in the gut mucosa of infected animals." (PMID 29028844, 2017). "Eosinophilia in lung tissue is driven partially by the recruitment of eosinophils to the lung mucosa and interstitium due to airway produced IL-5, as well as production of eotaxin (CCL11), eotaxin-2 (CCL24), and eotaxin-3 (CCL26)." (PMID 26346739, 2015).
Allergy (11 papers, 2010 to 2025). An allergy is an immune response or reaction to substances that are usually not harmful. "Normally, CCL26 plays a role in eosinophil migration during allergies, but we speculated that it might also be involved in the cell migration and motility of cancer cells." (PMID 34518591, 2021). "They found that the extract suppressed the release of mediators related to skin autoimmunity—IL-6 and IL-17C—and allergy—TSLP (thymic stromal lymphopoietin), IL-6, CCL26 (chemokine (C-C motif) Ligand 26), and MMP-9 (matrix metalloproteinase)." (PMID 40649262, 2025). "Eosinophils expressing the chemokine receptor CCR3 are attracted by the activation of the chemokine eotaxin family, which consists of eotaxin-1 (CCL11), eotaxin-2 (CCL24), and eotaxin-3 (CCL26), in allergic diseases." (PMID 39962262, 2025). "HVE inhibited the release of mediators involved in skin autoimmunity (IL-6 and IL-17C) and allergy (TSLP, IL-6, CCL26, and MMP-9) with a concentration-dependent fashion (IC50s < 25 μg/mL)." (PMID 36012541, 2022). "Mechanisms such as the epithelial cytokine production of CCL-26 (eotaxin-3) and the epithelial-derived alarmins TSLP and IL-33 increasingly focus on the interaction between the airway epithelium and immune cells in allergy research." (PMID 35563693, 2022).
atopic dermatitis (9 papers, 2017 to 2025). "Furthermore, the upregulation of disease-associated biomarkers, such as NELL2, CA2 and CCL26, indicates the prevalence of an immune response in the atopic dermatitis skin model." (PMID 36615633, 2023). "CCL26 mRNA expression was also significantly elevated when atopic dermatitis skin models were stimulated with histamine (m3) compared to the disease-associated skin model m2 without histamine stimulation (p < 0.001)." (PMID 36615633, 2023). "In atopic dermatitis, IL-31 induces chemotaxis, Ca2+ mobilization, release of reactive oxygen species, surface expression of adhesion molecules and CCL26 in eosinophils, which in turn release IL-31, contributing to the maintenance of the inflammatory infiltrate." (PMID 29156718, 2017). "The addition of histamine to the atopic dermatitis milieu enhanced mRNA expression of CCL26 significantly compared to the TH2 cytokine milieu without histamine (p < 0.01)." (PMID 36615633, 2023). "In accordance with the results of the mRNA expression obtained for primary keratinocytes, atopic dermatitis biomarkers such as NELL2, CA2 and CCL26 were significantly elevated in skin models m2 and m3 stimulated with TH2 cytokines (p < 0.05, p < 0.001, respectively)." (PMID 36615633, 2023).
colorectal cancer (9 papers, 2020 to 2025). A primary or metastatic malignant neoplasm that affects the colon or rectum. "Much less is known about the role of CCL26 in cancer, however elevated levels of this chemokine in tumors have been reported in later stage colorectal cancer and has been associated with worse prognosis." (PMID 33202734, 2020). "OChemokine ligand 26 (CCL26) levels were elevated in and positively correlated with stage III and IV colorectal cancer (CRC) tissues and were associated with a poor prognosis in CRC patients." (PMID 32286381, 2020). "Additionally, regenerated liver phosphatase 3 (PRL-3) has been found to promote the invasion and metastasis of colorectal cancer by upregulating CCL26 to induce TAMs infiltration." (PMID 38554160, 2024). "In oral squamous cell carcinoma (OSCC) and colorectal cancer (CRC), tumor cells exhibit high expression of CCL26, with elevated levels promoting epithelial–mesenchymal transition (EMT) and correlating with poorer survival." (PMID 41280721, 2025). "The concentrations of other parameters (CCL11, CCL26, CXCL14 and CA 19-9) were comparable to or even lower in the sera of patients with colorectal cancer compared to the group of healthy volunteers." (PMID 37240636, 2023). "The results from immunohistochemistry (IHC) analysis revealed that the levels of PRL-3 and CCL26 correlated positively with each other, and the levels increased in stages III and IV of colorectal cancer." (PMID 36213837, 2022).
hepatocellular carcinoma (9 papers, 2019 to 2025). A malignant tumor that arises from hepatocytes. "CCL26, for example, has been shown to be highly expressed in recurrent hepatocellular carcinoma (HCC), while CXCL2 is highly expressed in STK11-mutated NSCLC, which has a poorer response rate to ICIs." (PMID 35145511, 2021). "MDSCs preferentially infiltrate hypoxic regions driven by hypoxia-inducible tumor-derived factors, being C-C motif chemokine ligand 26 (CCL26) a clear example in hepatocellular carcinoma-associated MDSCs." (PMID 31535086, 2019). "Recently, bioinformatics-based prognostic models incorporating CCL26 have been developed for various cancers, including esophageal adenocarcinoma, hepatocellular carcinoma and OSCC have been constructed based on bioinformatics technology." (PMID 39931245, 2025). "Profiling of chemokines produced by a hepatoma cell line under hypoxia versus normoxia identified CCL26 and CCL28." (PMID 38786066, 2024). "On the other hand, hypoxia has been shown to increase MDSC recruitment to hepatocellular carcinoma by increasing CCL26/eotaxin-3 expression." (PMID 32781743, 2020). "Previous study reported that in Hepatocellular carcinoma, hypoxia-induced MDSC infiltration is dependent on CCL26, it was profoundly promoting angiogenesis, and tumor growth." (PMID 39931245, 2025). "In a model of hepatocellular carcinoma (HCC), HIF-1α upregulated the expression of chemokine (C-C motif) ligand 26 (CCL-26) in cancer cells, recruiting chemokine (C-X3-C motif) receptor 1 (CX3CR1) expressing-MDSCs to primary tumours and promoting HCC tumour growth." (PMID 31835751, 2019).
chronic rhinosinusitis (8 papers, 2019 to 2025). Chronic form of sinusitis. "As CCL26 attracts eosinophils, this interaction is supported by previous studies showing that CST1 progresses the migration of eosinophils and might play a role in the development of chronic rhinosinusitis." (PMID 38270326, 2024).
allergic asthma (7 papers, 2016 to 2025). A asthma with a basis in a pathological type I hypersensitivity reaction. "Our results may indicate that the overexpression of CST1 and CCL26 causes a more severe airway inflammation, particularly in allergic asthma, as well as an impaired immune system." (PMID 38270326, 2024). "We also identified that PLAG has an anti-inflammatory effect in an OVA-induced allergic asthma model by attenuating CCL26 expression from lung epithelial cells and eosinophil infiltration into the respiratory tract." (PMID 30622698, 2019). "The distinctive up-regulation of CCL26 makes this chemokine an important mediator for eosinophil recruitment in chronic allergic asthma." (PMID 27010397, 2016). "In this study, we investigated a commercially sourced, procyanidin A2 for in vitro efficacy in modulating interleukin-4 (IL-4)-induced CCL26 production relevant to allergic asthma." (PMID 27845745, 2016). "Allergic asthma is an inflammatory lung disease that is partly sustained by the chemokine eotaxin-3 (CCL26), which extends eosinophil migration into tissues long after allergen exposure." (PMID 27845745, 2016). "We confirmed IL-4 exposure induces CCL26 production in A549 cells, thereby modelling an aspect of airway inflammation of relevance to allergic asthma." (PMID 27845745, 2016). "Cyanidin-3-O-glucoside (C3G) prevented the progression of allergic asthma in a murine model through STAT6/GATA3 signaling suppression, whereas another cyanidin, procyanidin A2, reduced the expression of CCL26 in human keratinocytes via JAK1/STAT6 signaling." (PMID 35566102, 2022). "In this study, we discovered that PLAG can inhibit IL-4 induced CCL26 expression from epithelial cells by interfering with STAT6 signaling pathway, resulting in the control of eosinophil chemotaxis in an allergic asthma model." (PMID 27010397, 2016).
viral infection (6 papers, 2017 to 2023). "In addition, viral infections act in concert with IL-13 to induce the release of chemokines crucial to eosinophilic inflammation, including CCL26 and CCL5, from bronchial epithelial cells." (PMID 32120846, 2020). "Viral recognition receptors, such as toll-like receptor 3 (TLR3) expressed by epithelial cells, are activated to produce inflammatory cytokines and chemokines, including thymic stromal lymphopoietin (TSLP), CCL26, and CXCL8 when viral infection occurs." (PMID 32120846, 2020). "Thus, the inhibitory effects on TSLP and CCL26 expression even after viral infection are not common among glucocorticosteroid species, but linked with the pharmacological property of BUD." (PMID 32120846, 2020).
allergic rhinitis (5 papers, 2017 to 2025). Inflammation of the nasal mucous membranes caused by an IgE-mediated response to external allergens. "For eotaxin chemokines, CCL11 and CCL24 levels were increased in asthma and allergic rhinitis, and CCL26 levels were increased in allergic rhinitis and atopic skin inflammation." (PMID 33317619, 2020). "Moreover, in allergic rhinitis, NK cells were shown to infiltrate the epithelial layers and the stroma of nasal tissue in response to CX3CL1 and CCL26." (PMID 28503177, 2017).
melanoma (5 papers, 2017 to 2025). A malignant, usually aggressive tumor composed of atypical, neoplastic melanocytes. "However, in advanced melanoma, increased CCL26 levels have shown significant correlation with anti-PD1 antibody efficacy, suggesting potential benefits for these patients." (PMID 39931245, 2025). "We next assessed whether IL-33 induced the expression of eosinophil-attracting chemokines (CCL11, CCL24, CCL26, and CCL5) in melanoma cells and found significant up-regulation of CCL5 and CCL24." (PMID 31717819, 2019). "Neither CCL11 nor CCL26 were expressed by melanoma cells (data not shown)." (PMID 31717819, 2019). "Conversely, neoplastic cells were also negative for eotaxin-3 (CCL26) and other macrophage (heme oxygenase 1 [Mox macrophage], CD205 [DEC205], and CD208 [DC-LAMP]), Langerhans cell, follicular dendritic cell, epithelial cell, lymphocyte, melanoma, neuroendocrine, and mesenchymal cell markers." (PMID 33436014, 2021).
atherosclerosis (4 papers, 2014 to 2022). A disease characterized by the build-up of fatty material and calcium deposition in the arterial wall resulting in partial or complete occlusion of the arterial lumen. "In the HIVneg group, IL-27, IL-17C and CCL26 remained significantly associated with subclinical atherosclerosis following the regression analysis (p=0.041, p=0.012 and p=0.016, respectively), whereas IL-32θ and TNF-α were no longer significant." (PMID 33936102, 2021). "However, the subclinical atherosclerosis-associated plasmatic signature in the HIVneg population was different and marked with the upregulation of TNF-α and IL-27 and downregulation of CCL26 and IL-17C (p=0.02, 0.043, 0.011 and 0.021, respectively)." (PMID 33936102, 2021).
breast carcinoma (3 papers, 2020 to 2024). "Future work will be required to study the effects of CCL11 and CCL26 on M2 macrophage polarization and the subsequent effect on the migration and invasion of breast cancer cells." (PMID 38554160, 2024).
gastric cancer (3 papers, 2011 to 2025). A primary or metastatic malignant neoplasm involving the stomach. "In this investigation, we observed that PMN-MDSCs were up-regulated during stomach carcinogenesis, with gastric cancer (GC) cells secreting CCL26 to promote the infiltration of PMN-MDSCs into the TIME via the CX3CR1 receptor." (PMID 41280721, 2025). "Similar results were seen in a gastric cancer model, in which elevated levels of CCL17 and CCL26 in the tumor microenvironment demonstrated a positive correlation with the frequency of Foxp3 Treg, which can bind both these ligands with its CCR4 receptor." (PMID 22112546, 2011).
pulmonary fibrosis (3 papers, 2021 to 2025). Chronic progressive interstitial lung disorder characterized by the replacement of the lung tissue by connective tissue, leading to progressive dyspnea, respiratory failure, or right heart failure. "The implication of eotaxins in lung fibrosis are poorly understood, nonetheless, CCL11 is increased in experimental lung fibrosis while CCL11 deficient mice are protected and both CCL11, CCL24 and CCL26 are able to influence fibroblast behavior." (PMID 34093523, 2021).
urticaria (3 papers, 2016 to 2024). A vascular reaction of the skin characterized by erythema and wheal formation due to localized increase of vascular permeability. "Positive associations were found between D-dimer and CCL27, CCL17, and CCL26 in our study, indicating that D-dimer and chemokine might play a concomitant role in the pathogenesis of urticaria." (PMID 27057079, 2016). "CCL11, CCL17, CCL26, and CCL27 are implicated in the pathogenesis of urticaria." (PMID 27057079, 2016). "Among chemokines, CCL26 and CCL27 showed higher AUC (0.907 versus 0.906) values, providing maximum efficiency in prediction of moderate-to-severe urticaria with a sensitivity of 75.0% and 78.8% and specificity of 95% and 90.0%, respectively." (PMID 27057079, 2016). "In our study, serum levels of CCL11, CCL17, CCL26, and CCL27 increased significantly in both AU and CSU patients, indicating that elevated CCL11, CCL17, CCL26, and CCL27 are involved in the pathogenesis of urticaria." (PMID 27057079, 2016). "Moreover, CCL26 and CCL27 showed a high AUC, providing maximum efficiency in prediction of moderate-to-severe urticaria with high sensitivity and specificity." (PMID 27057079, 2016).
colon cancer (2 papers, 2021 to 2025). "According a report, in colon cancer CCL26 is involved in tumor progression by regulating the EMT signaling pathway." (PMID 39931245, 2025).
lung carcinoma (2 papers, 2025). "The IL-4 and IL-13 stimulated the lung cancer cell A549 to secrete CCL26." (PMID 41294800, 2025). "The IL-4 and IL-13 further stimulated the lung cancer cell A549 to secrete CCL26." (PMID 41294800, 2025).
metastatic disease (2 papers, 2020 to 2021). "The suppression of CCL26 by anti-CCL26 Ab in MG63 cells co-cultured with hMSCs resulted in a significant decrease in the growth of metastatic tumors in nude mice." (PMID 34518591, 2021).
oral squamous cell carcinoma (2 papers, 2025). "Our previous study demonstrated that CCL26 secreted by cancer-associated fibroblasts (CAF) promoted the invasive phenotype of oral squamous cell carcinoma (OSCC), however, more comprehensive clinical expression patterns of CCL26 and its role in immunotherapy remains ambiguous." (PMID 39931245, 2025).
osteosarcoma (2 papers, 2021 to 2025). A usually aggressive malignant bone-forming mesenchymal neoplasm, predominantly affecting adolescents and young adults. "It is assumed that CCL26, the expression of which increases when osteosarcoma and mesenchymal stem cells are coexistent, acts in a tumor-promoting manner." (PMID 34518591, 2021). "We unveiled the ability of osteosarcoma cells to use CCL26 as a factor to utilize normal cells for their growth, invasion and metastasis." (PMID 34518591, 2021). "Both the migratory and invasive abilities of osteosarcoma cells were enhanced by co-culturing with hMSCs accompanied by the addition of recombinant CCL26." (PMID 34518591, 2021). "The purpose of the study was to elucidate the involvement and significance of CCL26 in the tumor microenvironment and distant metastasis in osteosarcoma." (PMID 34518591, 2021). "To examine whether endogenous expression of IL13RA1-LOR1a can affect the ability of the cells to sense IL-4 or IL-13, we targeted its expression in U2OS osteosarcoma cells, which respond to stimulation by up-regulating CCL26." (PMID 40614216, 2025). "We next investigated the efficacy of CCL26 silencing against osteosarcoma tumor metastasis in vivo." (PMID 34518591, 2021). "Thus, we suggest that the cell-to-cell interaction of CCL26 enhanced not only proliferation but also motility of osteosarcoma cells." (PMID 34518591, 2021). "We used a co-culture model and discovered that the chemokine CCL26 might be involved in the progression of osteosarcoma cells." (PMID 34518591, 2021). "Therefore, it was supposed that the chemokine CCL26 was not only an inflammatory substance in osteosarcoma cells but also a very important humoral factor that promotes tumor progression." (PMID 34518591, 2021). "This indicates that osteosarcoma cells could increase CCL26 in co-operation with the surrounding normal cells to enhance their invasive potential for distant metastasis formation." (PMID 34518591, 2021). "Although CCL26 is a necessary factor for maintaining homeostasis, if it is also involved in promoting the development of malignant tumors via normal cells, controlling CCL26 may also lead to suppression of osteosarcoma progression." (PMID 34518591, 2021). "When human osteosarcoma cells (MG63) and human mesenchymal stem cells (hMSCs) were co-cultured and comprehensively analyzed for changes in each culture group, we found that the expression of chemokine (CC motif) ligand 26 (CCL26) was significantly enhanced." (PMID 34518591, 2021).
rheumatoid arthritis (2 papers, 2019 to 2023). A chronic, systemic autoimmune disorder characterized by inflammation in the synovial membranes and articular surfaces. "In the bootstrap resampling, we selected several important rheumatoid arthritis genes such as MMP genes (MMP1, MMP3), CCL genes (CCL3, CCL4, and CCL26), and IL genes (IL6, IL8, IL19, and IL24)." (PMID 31371761, 2019).